IL10 (interleukin 10)
Diseases named in the same sentence as IL10 in open-access papers (continued):
Sharing a sentence is not in itself a finding about the gene and the disease.
Disseminated intravascular coagulation (5 papers, 2020 to 2023). Disseminated intravascular coagulation is characterized by the widespread activation of coagulation, which results in the intravascular formation of fibrin and ultimately thrombotic occlusion of small and midsize vessels. "Our results of elevated IL-10/TNF-α and decreased IP-10/IL-10 ratios are similar to other studies looking at septic neonates with disseminated intravascular coagulation (DIC)." (PMID 32407417, 2020). "In the pig model, CO reduced the development of disseminated intravascular coagulation and inhibited serum levels of the pro-inflammatory cytokine IL-1 in response to LPS, whereas upregulated IL-10 levels." (PMID 33228260, 2020). "Previous studies report an elevated IL-6/IL-10 ratio in septic infants, and specifically in those with disseminated intravascular coagulation, which is often associated with fungal and Gram-negative bacterial infections that are known to elicit different cytokine responses." (PMID 32407417, 2020). "Biopsies obtained at the end of the study period did not demonstrate evidence of hyperacute rejection, disseminated intravascular coagulation (DIC), hyperinflammation, excessive cytokine release (IL-2, IL-6, IL-10, IL-13), or complement dysregulation." (PMID 38020483, 2023). "The ARDS group also had higher levels of IL-6, IL-8, and IL-10 than the non-ARDS group, and the levels of these cytokines correlated significantly with coagulation parameters and disseminated intravascular coagulation (DIC)." (PMID 34088317, 2021).
fasciolosis (5 papers, 2017 to 2025). "This elevation can benefit the host during Fasciola infection by reducing IL-10 production by specific CD4+ T cells and enhancing eosinophil degranulation triggered by specific antibodies." (PMID 40864124, 2025). "The immune response exerted during the early stages of fasciolosis is generally regarded as a mixed Th1/Th2 response displaying an increase of certain cytokines such as IFN-γ, IL-4, IL-10, and TGF-β." (PMID 38149297, 2023). "The immune response mounted during the early stages of fasciolosis is generally a mixed Th1/Th2 response with elevated levels of cytokines such as IFN-γ, IL-4, IL-10, and TGF-β." (PMID 38149297, 2023). "Although the mechanisms by which HO-1+ DCs or macrophages regulate the expression of IL-10 or oxidative responses during F. hepatica infection remain to be elucidated, targeting HO-1 to control fasciolosis could constitute an interesting alternative strategy to drugs or vaccines against fasciolosis." (PMID 28798750, 2017). "Fasciola hepatica infection of ruminants leads to non-resolving chronic infection, as patency develops, there is switching to a TGF-β and IL-10 led response." (PMID 28871261, 2017).
Flavivirus Infections (5 papers, 2022 to 2025). Infections with viruses of the genus FLAVIVIRUS, family FLAVIVIRIDAE. "Both species exhibited a balanced immune response, with TNF-α and IL-1β playing key roles in inflammation, while IL-10 and IL-13 were prominent in immunomodulation—patterns that are consistent with other flavivirus infections." (PMID 40143314, 2025). "IL-10 acts as an antagonist of TNFα-induced inflammation in a model of peripheral Flavivirus infection." (PMID 40003967, 2025). "Indeed, previous research has correlated Il10 with both protective and adverse outcomes of flavivirus infection." (PMID 35632766, 2022). "The significant differences in cytokine levels detected among ZIKV and DENV cases suggest that IL-4 and IL-10 may serve as differential immune indicators for acute ZIKV and acute DENV infections, respectively, when a flavivirus infection is considered." (PMID 37235332, 2023).
follicular lymphoma (5 papers, 2015 to 2023). Follicular lymphoma is a form of non-Hodgkin lymphoma characterized by a proliferation of B cells whose nodular structure of follicular architecture is preserved. "We also observed a trend of an association of high IL-10 levels with B-symptoms (p = 0.06) and with high-risk Follicular Lymphoma International Prognostic Index (FLIPI) (p = 0.05)." (PMID 32913559, 2020). "Our analyses of NHL subtypes corroborate results from studies of genetic polymorphisms because our study also found an association between IL-10 and DLBCL, as well as follicular lymphoma, lending credence to the hypothetical function of IL-10 in lymphomagenesis." (PMID 30873511, 2018). "A growing body of literature, as described in a recent meta-analysis, showed that IL-10 gene polymorphisms, especially 3575 T/A and 1082 A/G, were associated with increased NHL risk or its subtypes, including DLBCL and follicular lymphoma." (PMID 30873511, 2018). "DLBCL and follicular lymphoma showed associations with elevated IL-10 levels, and we observed no substantial differences in estimates when conducting pairwise comparisons by subtype (available online)." (PMID 30873511, 2018). "We identify several molecules that could contribute to the observed increased suppressive capacity of follicular lymphoma nodal tregs, including upregulation of CTLA-4, IL-10, and GITR, all confirmed by protein expression." (PMID 27228053, 2016).
gallstones (5 papers, 2023 to 2025). Solid crystalline precipitates in the biliary tract, usually formed in the gallbladder, resulting in the condition of cholelithiasis. "A study of subjects in China reported an association between levels of IL-6 and IL-10 and the risk of gallstone development." (PMID 38779446, 2024). "Given that IL-10 and IL-6 are inflammatory biomarkers related to DII calculations, this supports the existence of a direct association between DII values and gallstone development." (PMID 38779446, 2024). "For example, gallstone patients had higher levels of IL‐6, IL‐10 and IL‐12p70 than population‐based controls, and GBC patients had increased levels of C‐reactive protein (CRP), CCL20, IL‐16, sTNFRI and sTNFRII compared to gallstones controls." (PMID 39482824, 2025).
Hemophagocytosis (5 papers, 2015 to 2024). Phagocytosis by macrophages of erythrocytes, leukocytes, platelets, and their precursors in bone marrow and other tissues. "Of note, these manifestations are exacerbated by IL-10 blockade, and hemophagocytosis is observed only with IL-10 blockade." (PMID 36964620, 2023). "Furthermore, the authors described the protective role of IL-10 in this setting, showing that the inhibition of its signal and/or the IL-10 receptor led to the development of hemophagocytosis." (PMID 33802085, 2021). "Hemophagocytosis is associated with more severe disease, and may be part of a non-specific response to severe systemic inflammation, independent from the action of IFN-γ, but inhibited by IL-10." (PMID 26610523, 2015). "Hemophagocytosis, an important MAS symptom, was only observed after blocking IL-10, pointing to a protective function of IL-10 in the syndrome." (PMID 26610523, 2015). "Previous studies described that hemophagocytosis is not induced in the spleen of MAS mice and blocking of IL-10 was required along with CpG administration for induction hemophagocytosis in the spleen." (PMID 38558807, 2024). "When IL-10 signalling was maintained, the administration of the TLR9 agonist resulted in a milder HLH in wild-type (WT) mice, with less severe hepatitis and lack of hemophagocytosis." (PMID 33802085, 2021).
hemorrhagic fever (5 papers, 2011 to 2022). An infectious disease caused by certain viruses or bacteria that can damage the walls of tiny blood vessels, making them leak, and can hamper the blood's ability to clot and cause severe, life-threatening illness. "It is noteworthy that elevated levels of IL-6, IL-8, IL-10, G-CSF, and TNF-alpha, which were observed in MACV-infected STAT-1 knockout mice, are correlated with the severity of human Argentinean hemorrhagic fever, caused by the related Junín virus." (PMID 21672221, 2011). "However, pathological cytokine responses including IFNγ, IL-6, IL-10, TNFα, and IP-10, all of which are elevated in AB6 mice during fatal Ang71 infection, have been implicated in inducing vascular permeability with the onset of hemorrhagic fever after infection with the related Dengue virus (DENV)." (PMID 27463517, 2016).
herpes zoster (5 papers, 2014 to 2025). A common dermal and neurologic disorder caused by reactivation of the varicella-zoster virus that has remained dormant within dorsal root ganglia, often for decades, after the patient's initial exposure to the virus in the form of varicella (chickenpox). "Similar to this report, other studies found that the IL-10-1082 G allele was significantly higher in herpes zoster patients." (PMID 35207552, 2022). "Interestingly, clinical data from adult patients with herpes zoster or VZV indicate that high levels of IL-10 can be detected in body fluids at the time of infection and have predictive value for the severity of infection." (PMID 36314824, 2022). "The fluid in skin blisters and peripheral blood of herpes zoster patients has low levels of the Th1 cytokines interleukin (IL)-2 and tumor necrosis factor-α and high levels of the Th2 cytokines IL-10 and IL-4 compared with the levels of these cytokines in samples from a control group." (PMID 32944021, 2020).
hypercoagulability (5 papers, 2016 to 2024). "For instance, IL-10 polymorphism, RAAS, FOXP3, thrombophilia, and NOS3 were found to be associated with an increased risk of PE." (PMID 39194706, 2024). "For further evaluating whether XFC can alleviate inflammation and hypercoagulability in AA rats, RA diagnostic indicators (RF and CRP), inflammatory factors (IL-6and IL-10), and coagulation indicators (FBG and DD) were detected." (PMID 39376558, 2024).
hyperthyroidism (5 papers, 2016 to 2025). Overactivity of the thyroid gland resulting in overproduction of thyroid hormone and increased metabolic rate. "For example, genetic variants of TNF-α, IL-1, IL-6, and IL-10 have been reported to increase the risk of hyperthyroidism." (PMID 34567510, 2021). "The immunohistochemical analysis presented both hyperthyroidism and hypertrophic cardiomyopathy groups with a significant loss of contractile protein (desmin) and an increase in interleukin-10, a cytokine characterised by anti-inflammatory properties and activated in myocardial remodelling." (PMID 40564271, 2025). "It was reported that NF-κB is activated by hyperthyroidism, which is crucial for controlling the genetic transcription and encoding of inflammatory cytokines including IL-10, IL-4, TNF-α, and IL-6 that, in turn, promote NO, lipid peroxidation and free radical generation." (PMID 37020549, 2023). "However, Asians show different genetic polymorphisms for hyperthyroidism risk: IL-1α at 889 C/T, IL-1β at 511 C/T, IL-6 at 174 G/C, IL-6 at 572 G/C, and IL-10 at 1,082 A/G polymorphisms." (PMID 34567510, 2021). "The level of the pro-inflammatory markers (TNF-α, IL-1, IL-4, IL-6, and IL-10) in the hyperthyroidism group of rats was much higher than that of the healthy animals, whereas the level of the apoptotic marker (CD4+) was noticeably lower." (PMID 37020549, 2023). "Our findings revealed that, despite median left ventricular dimensions not being significantly different from ones observed in healthy animals, cats with hyperthyroidism exhibited similar alterations in desmin and interleukin-10 expression to those seen in HCM-affected cats." (PMID 40564271, 2025). "In terms of outcome, TNF-α, IL-6, IL-10, IFN-γ, and relapse rate were added in this study to comprehensively evaluate the efficacy of the PVL preparations in intervening in hyperthyroidism." (PMID 40083379, 2025). "The findings showed that hesperidin significantly modulated hyperthyroidism deteriorations, this was evidenced by a remarkable decline in serum T4, FT4, T3, FT3, TNF-α, IL1β-, IL4-, IL-6, and IL-10 levels, with a minor increase in TSH and significant raise in CD4+ level." (PMID 37020549, 2023). "Interestingly, treatment of hyperthyroidism-modeled group with hesperidin therapy dramatically decreased blood levels of TNF-α, IL-1, IL-4, IL-6, and IL-10 while sharply increasing CD4+ level close to healthy controls." (PMID 37020549, 2023). "Also opposite to the results obtained in TRs KO mice, hyperthyroidism resulted in increased hepatic levels of IL-6 and SOCS3 transcripts in response to 5 mg/kg LPS or 20 mg/kg LPS, while TNFα and IL-10 mRNAs remained unchanged." (PMID 27484112, 2016).
Hyponatremia (5 papers, 2015 to 2025). An abnormally decreased sodium concentration in the blood. "Based on this, the association between hyponatremia, which is considered a marker of kidney disease severity in HUS patients, and IL-10 production by monocytes would need further experiments to evaluate possible direct mechanisms." (PMID 37425258, 2023).
immunotoxicity (5 papers, 2016 to 2024). "In accordance, feeding AFB1-contaminated diets resulted in heightened expression of IL-6, IFN-γ, and IL-10; impaired lymphocyte; and delayed cell-mediated immune response, while Se deficiency aggravated AFB1-induced immunotoxicity." (PMID 38147231, 2024). "Interestingly, in addition to inflammatory responses, which were considered to be the main cause of immunotoxicity, immunosuppressive responses, such as the expansion of ICOS+ Treg cells and production of immunosuppressive cytokine, IL-10, occurred concurrently." (PMID 33193321, 2020).
intestinal parasitic infections (5 papers, 2009 to 2023). "Here, intestinal parasite infections (IPIs) and blood filariasis were associated with decreased Th1 (IL-6) and Treg (IL-10) responses." (PMID 35421083, 2022). "Intestinal parasite infection in pregnancy was independently associated with lower levels of IL-10." (PMID 31214627, 2019). "With respect to maternal infections, the final model of multiple logistic regression in our study showed that intestinal parasitic infections especially protozoa influenced the relationship between maternal and infant IL-10 and IFN-γ production in responses to PHA." (PMID 19898617, 2009). "Mothers with high IL-10 in response to LPS had children with high IL-10 in response to LPS, but the magnitude of association was much smaller and no longer significant when maternal intestinal parasitic infections and village of residence were adjusted for." (PMID 19898617, 2009).
intestinal tumors (5 papers, 2016 to 2023). "In CAC, Il10-deficient mice were shown to be more susceptible to spontaneous intestinal tumor development compared with WT animals." (PMID 27148488, 2016). "The Il-10 reduction is consistent with other studies that have shown that T cell-restricted ablation of IL-10 increased the number of polyps by promoting the accumulation of microbes and eosinophils and IL-10 deficient mice are more susceptible to spontaneous intestinal tumour development." (PMID 30559928, 2018). "In the ApcΔ468 model, T cell-restricted ablation of IL-10 increased the number of intestinal polyps by promoting the accumulation of microbes and eosinophils in intestinal tumors." (PMID 27148488, 2016). "Additionally, M13–NL treatment enhanced the composition of the intestinal microbiota, bringing it closer to that of low-inflammation IL10−/− mice, and modestly increased the presence of microbial species in intestinal tumors." (PMID 37765299, 2023). "However, in the APCmin−/+ model of sporadic CRC, IL-10 seemed to be responsible for the capacity of adoptively transferred Treg cells to inhibit intestinal tumor development and growth." (PMID 36428508, 2022).
laryngeal carcinoma (5 papers, 2009 to 2024). Carcinoma that arises from the laryngeal epithelium. "Association between IL-10 genotypes and the development of head and neck, nasopharyngeal and laryngeal cancers." (PMID 30762321, 2019). "Regarding the evaluation of serum levels of cytokines in patients with laryngeal cancer, a study was conducted in Southwest of Iran in levels of IL-10 in patients with laryngeal cancer and the associated metastases." (PMID 26082901, 2015). "This study showed differences, especially in the level of cytokines (IL-4, IL-13 and IL-10), depending on the model of direct and indirect interactions between laryngeal cancer cells and macrophages." (PMID 39057050, 2024). "Two-loci IL-10 haplotype distribution in head and neck, nasopharyngeal and laryngeal cancer cases and controls." (PMID 30762321, 2019). "We assessed the serum levels of cytokines (IL–1, IL–2,IL–4, IL–6, IL–8, IL–10, IFN–gamma, TNF–alpha, GM–CSF), chemokines (MCP–1 and MIP–1alpha)and growth factors (VEGF and bFGF) in laryngeal cancer patients before, during and after surgery." (PMID 20108543, 2009).
lymphedema (5 papers, 2009 to 2024). Excess fluid collection in tissues, causing swelling. "Recent studies have demonstrated that circulating levels of TNF-α, IL-10 and monocytes in lymphedema patients was significantly reduced following CDT when compared to control participants." (PMID 38612716, 2024). "Separate studies have corroborated these findings, noting correlation between IL-10, TNF-α, and TGFβ-1 levels and lymphedema-related factors following lymph node transfer." (PMID 38612716, 2024). "Patients with lymphedema exhibited Th2 or IL-10 responses to filarial antigen that were no different than the Th2 or IL-10 responses seen in INF patients." (PMID 19381284, 2009).
lymphoproliferative disorders (5 papers, 2018 to 2024). "Previous study reported that increased IL-10 in patients with lymphoproliferative disorder causes elevated triglycerides, low LDL-C and HDL-C deficiency, and IL-10 is thus a potent modulator of lipoprotein levels." (PMID 29895283, 2018). "In KSHV, elevated levels of IL-10 are believed to contribute to KSHV persistence in and pathogenesis of KSHV-associated lymphoproliferative disorders." (PMID 35914074, 2022). "Among them, IL-10, an immunosuppressive cytokine contributing to viral persistence in and pathogenesis of KSHV-associated lymphoproliferative disorders (33, –, 35), showed a consistent induction by KSHV reactivation (>1.5-fold) in KDM4A-WT-, but not in KDM4A-K471R-expressing cells." (PMID 35914074, 2022).
membranous nephropathy (5 papers, 2016 to 2025). "Significantly higher frequency of CD4+/CXCR5+, CD4+/CXCR5+/ICOS+ and CD4+/CXCR5+/PD-1+ TFH cells, and higher serum levels of IL-17A, IFN-γ, IL-2, IL-10, IL-4 and IL-21 were detected in hepatitis B virus-associated membranous nephropathy patients compared to the healthy controls." (PMID 28770269, 2018). "In HBV-associated membranous nephropathy (HBV-MN), the percentage of B10 cell and IL-10 levels were significantly higher than in healthy controls." (PMID 40904455, 2025). "The opposite result showed a positive correlation between CD38+CD19+ B cells and IL-10+CD19+ B cells and hepatitis B virus-associated membranous nephropathy." (PMID 31649905, 2019). "However, among patients with hepatitis B virus-associated membranous nephropathy (HBV-MN), higher proportions of CD5+CD19+ and IL-10+CD19+ B cells and serum IL-10 levels have been reported." (PMID 34108975, 2021).